ASPG (asparaginase)
Diseases named in the same sentence as ASPG in open-access papers (continued):
Sharing a sentence is not in itself a finding about the gene and the disease.
cancer (continued). "Asparaginase activity is required to deamidate asparagine to aspartate, an essential amino acid for proliferating mammalian cells (e.g., cancer cells) and as a neurotransmitter." (PMID 35916501, 2022). "The Children's Cancer group (CCG) conducted a similar phase II trial comparing native E. coli derived asparaginase to pegaspargase with the main goals of assessing differences in safety and antibody production." (PMID 35844739, 2022). "Our observations indicated that the effect of asparaginase differs between cell types, and the prepared ASNase enzyme can inhibit the reproduction of cancer cells selectively." (PMID 35690915, 2022). "Asparaginase represents one of the first examples of a therapeutic approach targeting AA metabolism by exploiting AA auxotrophy in cancer, and has resulted in notable improvement of paediatric ALL outcomes." (PMID 34292410, 2021). "This event is attributed to ADI being a nonhuman protein and thus warrants caution for toxicity although the prevalence has been low, especially when compared to pegylated asparaginase, another anti‐cancer enzyme therapy." (PMID 33787078, 2021). "The success of asparaginase therapy has prompted the development of additional therapeutics designed to exploit cancer AA dependencies." (PMID 34292410, 2021). "Apart from asparaginase, arginine deiminase, arginase, some other amino acid enzymes have been recently developed for cancer therapy, including methionase, lysine oxidase, phenylalanine ammonia lyase, and glutaminase." (PMID 33510635, 2020). "Deprivation of amino acids through dietary regulation and application of enzymes, such as Asparaginase, have been in vogue in cancer therapies." (PMID 32927667, 2020). "Asparaginase is a well-known anticancerous enzyme used as a chemotherapeutic agent in other cancer treatment, so ZnO NPs carrying asparaginase, further increase the specificity and stability when given in combination with paclitaxel and daunorubicin." (PMID 31661003, 2019). "It has been shown that asparaginase also has glutaminase activity, which can kill cancer cells, raising the question of how important glutamine depletion is to the induction of leukaemic cell death." (PMID 30578463, 2019). "Another example of pioneer cancer therapy targeting metabolism is depletion of asparagine (and glutamine) using asparaginase." (PMID 29262552, 2017). "On the other hand, asparaginase treatment triggers reprogramming of cancer cell metabolism toward fatty acid oxidation, providing the support of tricarboxylic acid (TCA) cycle intermediates." (PMID 29262552, 2017). "Although asparaginase is effective as a therapeutic for cancers that obtain the majority of their asparagine from the environment, cancers that are capable of synthesizing asparagine de novo via ASNS are less responsive to asparaginase therapy." (PMID 27126896, 2016). "Experts comment that patient volume in adult oncology is not commensurate with the intricate needs of these regimens, including strong clinic infrastructure necessary for patient support and a crucial medication (asparaginase), which is rarely used in common adult cancers and has unique toxicities." (PMID 40238217, 2025). "After identifying a common dependency of cisplatin‐resistant cancer cells upon extracellular glutamine, we then evaluate the utility of the long‐standing anti‐leukemic therapy asparaginase (ASNase)—which possesses both asparaginase and glutaminase activity—as a potential approach." (PMID 40784667, 2025). "Coculture killing assay showed ASPG-OE CAR-T cells exhibited increased killing efficacy against ASNS-OE cancer cells by enhancing the expression of granzyme B, interferon gamma, and tumor necrosis factor alpha, whereas ASPG-knockout (KO) CAR-T cells showed decreased cancer cell lysis efficiency." (PMID 40808257, 2025).
cancer (continued). "Previously, we have developed a strategy to enhance the ability of L-ASNase to penetrate cancer cells by conjugating asparaginase with cationic polymers such as derivatives of cationic polymers, like chitosan, polyethyleneimine (PEI), PEG–chitosan, PEI-g-PEG, etc.." (PMID 40724997, 2025). "The results also imply that asparaginase could be particularly beneficial in targeting cancer cells that are resistant to conventional therapies." (PMID 40402326, 2025). "Specific ASNS inhibitors are currently in development and may offer effective future treatment strategies for CRC, and indeed other cancers, in combination with asparaginase and/or autophagy inhibition." (PMID 39332495, 2024). "Thus inhibition of telomerase by RrA is characterized by a dual (anti‐asparaginase and anti‐telomerase) anti-cancer effect in one protein." (PMID 37679807, 2023). "Asparaginase has an inhibitory effect on protein synthesis in cancer cells, it is hypothesized that muscle protein synthesis in muscle cells may also be compromised." (PMID 38069550, 2023). "Asparagine auxotrophy not only has the apparent implication in heightened sensitivity to asparagine depletion and, therefore, to asparaginase therapy, but also implies the cancer cells’ tight reliance on external supplies of the amino acid even under normal growth conditions." (PMID 36405587, 2022). "Examples of these strategies can be found by examining the asparaginase dosing regimens of the three major pediatric cancer consortia in North America, the Children's Oncology Group (COG), Dana Farber Cancer Institute (DFCI) and St Jude Children's Research Hospital (SJCRH)." (PMID 35844739, 2022). "Therefore, asparaginase (ASNase), which catalyzes the deamination of asparagine to aspartate, has been used to decrease extracellular asparagine in asparagine dependent cancers." (PMID 34685569, 2021). "Furthermore, asparaginase, an enzyme that catalyzes asparagine into aspartate and ammonia, has been used to treat cancers including acute lymphoblastic leukemia, acute myeloid leukemia and non-Hodgkin's lymphoma." (PMID 32587832, 2020). "However, asparaginase resistance is reported in some cases of cancers and the use of ASNS inhibitors has been proposed and is currently in the development process." (PMID 32587832, 2020). "In the field of cancer treatment, there are already some good enzyme drugs used in chemotherapy, such as arginine deaminase and asparaginase, which utilize PEGylation to increase the half-life of exogenously infused recombinant enzymes and reduce immunogenicity." (PMID 33374889, 2020). "A recent study showed a potential strategy to improve the response of cancer cells to asparaginase." (PMID 30813354, 2019). "Considering that cancer cells lack asparaginase activity to convert asparagine to aspartate and that aspartate has poor cell permeability preventing exogenous intake, therapeutic aspartate suppression could be useful to treat cancer." (PMID 31835679, 2019). "Erwinia asparaginase is an FDA-approved enzyme drug for treatment of select cancers." (PMID 28358370, 2017). "Hence, the cytotoxicity of asparaginase purified from E. cloacae was tested against panel of human cancer cell lines, HL-60, MOLT-4, MDA-MB-231 and T47D." (PMID 26891220, 2016). "The potential of asparaginase in cancer treatment was first reported in 1953 (Kidd, 1953)." (PMID 27330530, 2016). "Co-treatment with asparaginase and GCN2 inhibition or deletion synergize with asparaginase against multiple cancer cell types." (PMID 39319345, 2024). "Moharib, (2018) reported that asparaginase from Vigna unguiculata killed 50% of HELLA, HCT116 and HEPG2 cancer cell lines." (PMID 38015853, 2023). "Limited asparaginase efficiency in fighting many solid cancers, such as prostate and ovarian cancer, is believed to be due to the medium/high expression of ASNS in these cancer types." (PMID 36405587, 2022).
cancer (continued). "It is currently being examined clinically in other cancer types (NCT03026517), and our data show that this can be potentiated by asparagine depletion using asparaginase." (PMID 36411320, 2022). "While asparaginase is a critical component of ALL/LBL therapy across all major pediatric and AYA cancer consortia, the dosing and administration schedule differs between groups." (PMID 35844739, 2022). "One clinically utilised strategy targeting AA dependency is the use of asparaginase in the treatment of acute lymphoblastic leukaemia (ALL), which results in a depletion of exogenous asparagine and subsequent cancer cell death." (PMID 34292410, 2021). "The enzyme also possesses off-target residual glutaminase activity and several studies have indicated that both its asparaginase and glutaminase activity are required for antileukemic efficacy depending on the expression of ASNS by the cancer." (PMID 34277440, 2021). "Our results support asparagine as an important contributor to cancer cell growth and suggest strategies for improving efficacy of asparaginase and GLS inhibitors as cancer treatments." (PMID 27126896, 2016). "Asparaginase, a Food and Drug Administration (FDA)-approved enzyme therapeutics for cancer therapy, has been used to treat ALL since the early 1970s and induces a 60% of complete remission (CR) rate as a monotherapy." (PMID 25738356, 2015). "Exploiting the dependency of cancer cells on amino acid availability offers therapeutic avenues, for instance, through the use of asparaginase, which depletes the non-essential amino acid asparagine." (PMID 40131931, 2025). "Still, asparaginase is an attractive anti-cancer drug, as its side effect profile does not overlap with the toxicities of many other conventional chemotherapy drugs." (PMID 33499165, 2021). "This means that there are several potential intervention points available for treating the side-effect of asparaginase, without interfering with its primary effect on the cancer cells." (PMID 27377732, 2016). "However, the number of participants with solid experience in the management of pediatric cancer and accounting for 90% of hospitals in which children with ALL are treated in Spain, ensures that the survey was able to capture real‐world data of asparaginase activity monitoring in clinical practice." (PMID 36307379, 2023). "Although the increase in plasma serine observed after asparaginase is not necessarily a neoplastic-dependent phenomenon, cancer cells may be able to take advantage of increased serine to fuel cell proliferation." (PMID 36578934, 2022). "The introduction of the A6E mutation to the ASNS gene could be an alternative approach to impede the attempt of cancer cells to stimulate the expression of ASNS, such that the ALL patients would not develop any resistance to the asparaginase treatment." (PMID 33916846, 2021).
tumor (51 papers, 2010 to 2025). "Hematopoietic inhibition early in chemotherapy, vascular endothelial cell damage from tumor cell infiltration, and asparaginase‐associated coagulopathy are all high‐risk factors for bleeding during the induction remission phase." (PMID 40842042, 2025). "For example, UQCRH gene expression in tumor cells was positively associated with the sensitivity of asparaginase, ifosfamide, carmustine, lomustine, and oxaliplatin but negatively associated with everolimus and rapamycin." (PMID 36105252, 2022). "In our cohort, thromboprophylaxis was performed in patients who were considered to be at a high risk of VTE based on their genetic risk profile, tumor site, or use of asparaginase medication." (PMID 25317335, 2014). "Another consideration is whether certain tumours might respond better to bacterial therapy with an asparaginase-deficient STm, for example tumours with less reliance on c-Myc." (PMID 39558103, 2024). "However, for children with ALL in the intermediate-high risk group, the EFS of children with AAP with interrupted asparaginase therapy was significantly lower than that of children who were re-exposed, with a 5.96-fold increased risk of tumour relapse or death." (PMID 39439952, 2024). "For example, GZMA and AIM2 gene expression in tumor cells was positively associated with increased drug sensitivity to nelarabine, dexamethasone decadron, fluphenazine, arsenic trioxide, procarbazine, olaparib, fludarabine, simvastatin, cyclophosphamide, and asparaginase." (PMID 34721986, 2021). "Compared to the control group, the asparaginase, anti-PD-L1, and combination therapy groups all significantly inhibited tumor growth, with the most pronounced therapeutic effect observed in the combination therapy group." (PMID 41229436, 2025). "Subsequently, the in vitro effect of asparaginase on the viability of MFC tumor cells was determined using the CCK-8 assay after treatment for 24 hours with varying concentrations (0, 1, 2, 4, 6, 8 IU/ml)." (PMID 41229436, 2025). "When combined with autophagy inhibitors, a significant enhancement in tumor response to asparaginase was observed." (PMID 41316157, 2025). "The tumor growth rate was significantly slower in the Asparaginase + anti-PD-L1 group and the Asparaginase + anti-PD-L1 + anti-CD4 group compared to the Control group." (PMID 41229436, 2025). "Collectively, these results indicate that combining anti-PD-L1 antibody with asparaginase significantly enhances the in vivo anti-tumor effect." (PMID 41229436, 2025). "This is in contrast to a recent report that single-agent E.coli-derived asparaginase was unable to inhibit PDAC tumor growth, which confirms the value of utilizing a crisantaspase, which targets both asparagine and glutamine." (PMID 38951899, 2024). "Asparaginase deletion was able to restore, or even enhance, IL-2 production in our co-culture model and within primary tumours." (PMID 39558103, 2024). "Restoration of c-Myc by deletion of the bacterial asparaginase ansB reinvigorated T cell activation, but at the cost of decreased metabolic control of the tumour by STm." (PMID 39558103, 2024). "To further validate that asparaginase was the causative agent of T cell dysfunction, and to determine whether this effect occurs broadly amongst bacterial vectors, we tested an attenuated Listeria monocytogenes (Lm) and E. coli Nissle (EcN) vector in our tumour organoid model." (PMID 39558103, 2024). "In accordance, stimulation of primary tumours from infected mice ex vivo exhibited a reinvigorated T cell IL-2 response when asparaginase was deleted from the bacterium." (PMID 39558103, 2024). "The combination of Asparaginase with ETC inhibition is an effective therapy to inhibit tumor growth." (PMID 39272889, 2024). "Asparaginase starves the tumor of a metabolic nutrient that is essential to their growth in a type of treatment called amino acid depletion therapy." (PMID 36678770, 2022).
tumor (continued). "An ATTEMPTS system trial to deliver asparaginase to tumor cells demonstrated increased cell permeability." (PMID 35744957, 2022). "A recent report demonstrated enhanced combinatorial anti-tumor activity of ETC inhibition with dietary asparagine restriction with asparaginase, through depletion of exogenous asparagine that communicates active respiration to ATF4 and mTORC154." (PMID 35589701, 2022). "Active enzymes for AADT (e.g., asparaginase, arginine deiminase, arginase, methioninase, cysteinase, etc.)deprive cancer cells of amino acids necessary for tumor growth." (PMID 36678770, 2022). "The difference between the means of survival time of the tumor injected mice and the asparaginase-encapsulated tumor injected group constituted 1.7 days in favor of the latter." (PMID 34833427, 2021). "Our previous study found a significant increase in expression of BCYRN1 in ENKTCL tumor tissue when compared to normal natural killer (NK) cells, especially in those with acquired resistance to asparaginase." (PMID 33391513, 2021). "Asparaginase kills ENKTCL by depriving tumor cells of L-asparagine, an important nutrient factor, which cannot be efficiently synthesized by ENKTCL cells due to their reduced L-asparagine synthetase (ASNS) level." (PMID 33391513, 2021). "Enzymatic depletion of plasma cystine and cysteine—similar to the approach used for asparagine with asparaginase—can also suppress tumor growth." (PMID 31096630, 2019). "While the clinical utility of asparaginase makes it clear that asparagine is essential for tumor growth, the importance of asparagine beyond protein synthesis is less understood." (PMID 31096630, 2019). "The average values of tumor volume for the control, asparaginase, CQ, the combination of asparaginase and CQ, and temozolomide after 19-day treatment were 887 mm3, 702 mm3, 993 mm3, 126 mm3 and 0, respectively." (PMID 29207624, 2017). "The use of enzymes to deprive neoplasm of essential nutrients offers a promising approach for treatment of tumor malignancies; asparaginase is cornerstone of them." (PMID 26891220, 2016). "Asparaginase is a well known chemotherapeutic enzyme, universally used in the treatment protocols of various neoplasms, particularly of lymphoid origins." (PMID 26891220, 2016). "The importance of asparagine for tumour growth has been demonstrated by the effectiveness of extracellular asparaginase in treating low-ASNS-expressing leukaemia." (PMID 27126896, 2016). "The presence of therapeutic asparaginase deprives tumor cells of an important growth factor by hydrolyzing L-asparagine into L-aspartic acid and ammonia, afterwards tumor cells fail to survive because of their reduced ASNS levels." (PMID 25738356, 2015). "To examine this possibility, we treated subgroups of animals transplanted with shASNS- or shLUC-tumor cells with asparaginase (1500 IU/kg;) by daily intraperitoneal (IP) injection." (PMID 26499495, 2015). "Daily exposure to asparaginase did not change the latency of shLUC-tumors (p = 0.5); however, asparaginase treatment significantly prolonged tumor latency in mice implanted with shASNS-RMS cells (p<0.001)." (PMID 26499495, 2015). "Asparaginase-sensitive malignant tumor cells are thought to express relatively low levels of ASNS and thus depend on the available of extracellular asparagine for their survival." (PMID 25738356, 2015). "Asparaginase treatment was initiated on the day of tumor cell injection and continued for 35–41 days." (PMID 26499495, 2015). "In summary, asparaginase as a single agent is effective at reducing tumor growth and increasing survival when compared to the untreated cohort." (PMID 20146790, 2010). "The average tumor volumes at day 65 for the asparaginase plus rapamycin cohort (1570 ± 378 mm3) and the rapamycin cohort (1349 ± 302 mm3) are similar." (PMID 20146790, 2010).